AR (androgen receptor)
Diseases named in the same sentence as AR in open-access papers (continued):
Sharing a sentence is not in itself a finding about the gene and the disease.
breast carcinoma (1,130 papers, 1996 to 2026). "Studies have shown that AR expression in human breast cancer is present in a subset of patients and has been associated with a less aggressive tumor phenotype and better clinical outcomes." (PMID 40286049, 2025). "In a cohort of over 1100 breast cancer patients, AR expression and nuclear localization were associated with lower tumor size and grade, leading to a better prognosis in ER-positive tumors." (PMID 40023399, 2025). "In many cases, AR expression has been linked to a more favorable prognosis, particularly in estrogen receptor-positive (ER-positive) breast cancer subtypes." (PMID 40286049, 2025). "In breast cancer, elevated ERα expression with low AR increased the risk of cancer-related deaths by 4.6-fold." (PMID 40023399, 2025). "This parallels findings in human breast cancer, where AR expression is similarly associated with more aggressive or advanced stages of the disease in certain breast cancer subtypes." (PMID 40286049, 2025). "The AR variants in the 3 cases that were reported to have breast cancer were located in the DNA binding domain (R608Q, R609K), which is known to impact the transcriptional activity of AR." (PMID 39213311, 2025). "The androgen receptor (AR) and estrogen receptor (ER) are frequently overexpressed or mutated in prostate and breast cancers, respectively." (PMID 40227962, 2025). "The available literature on the association of the AR-positive status and disease outcome in breast cancer patients is inconclusive." (PMID 40150035, 2025). "In human breast cancer, AR expression has been linked to various clinical outcomes and tumor characteristics." (PMID 40286049, 2025). "In HER2+ ER− breast cancer cells, the inhibition of AR decreased cell growth and caused a reduction in HER2 phosphorylation and the ERK/AKT growth pathway." (PMID 40023399, 2025). "MetaCore analysis also revealed that pro-oncogenic actions of the androgen receptor were associated with breast cancer." (PMID 40278313, 2025). "The onset, spread, and management of breast cancer are closely linked to the nuclear receptor family of transcription factors, including the estrogen receptor (ER), androgen receptor (AR), and progesterone receptor (PR)." (PMID 39857438, 2025). "Our study highlights that AR expression is significantly associated with HR+ breast cancers and better differentiation, making it a valuable marker for patient stratification." (PMID 40734715, 2025). "A previous study reported that a higher percentage of AR-positive breast cancer cells was associated with a better OS." (PMID 40150035, 2025). "Conversely, in canine mammary tumors, higher levels of androgen-receptor expression have been linked to a more aggressive phenotype and poorer prognosis." (PMID 40286049, 2025). "In the previous section, we primarily investigated potential association between AR PGx-eQTLs and prognosis of endocrine therapies in breast cancer using data from three BC GWAS we published." (PMID 38965614, 2024). "While the role and mechanistic pathways associated with ER signaling in breast cancer have been comprehensively described, understanding of AR signaling in this disease is much more limited." (PMID 38317241, 2024). "Terms such as “breast cancer,” “biomarkers,” “androgen receptor,” “invasion,” and “metastasis” are directly linked to tumor growth, spread, and treatment." (PMID 39355131, 2024). "We used human breast cancer‐derived cells with high, low, and very low expression levels of AR to examine apoptosis caused by a novel peptide that targets ARs." (PMID 37903548, 2024). "Lower expression of the LRRC8A gene is associated with reduced sensitivity of breast cancer patients to chemotherapy drugs such as BX-912, AR-42, AT-7519, BHG712, CAL-101, and CAY10603." (PMID 38388382, 2024). "The existing knowledge regarding the association of androgen receptor expression with clinicopathological factors of breast cancer is also limited." (PMID 39497884, 2024).
breast carcinoma (continued). "On the contrary, CYTlow androgen receptor (AR) and estrogen receptor (ER)-positive breast cancer patients were associated with low infiltration and CD8+ T cells and lower overall anticancer immunity and survival." (PMID 38612436, 2024). "The distribution of ER, PR, and AR across the B classification emphasizes the distinct hormone receptor profiles associated with different B categories in breast cancer, with all findings showing strong statistical significance." (PMID 39456566, 2024). "The expression of constitutively active truncated AR splice variants in breast cancer is a possible mechanism contributing to treatment resistance." (PMID 38339092, 2024). "This study analyzed AR expression and its association with various clinicopathological factors of breast carcinoma." (PMID 39497884, 2024). "The androgen receptor is tightly linked to the ER in breast cancer, the two receptors compete for DNA binding sites, and their signaling pathways cross talk at multiple levels." (PMID 38982086, 2024). "Many investigations have shown that AR expression in breast cancer, particularly in the TNBC subtype, has been linked to an overall better outcome." (PMID 40860264, 2024). "The androgen receptor (AR) is also highly expressed in breast cancer cells, and intratumoral androgens are implicated in tumor progression and resistance to endocrine therapy." (PMID 39682229, 2024). "Nonetheless, three genes (CNTNAP2, EHF, KDM4B) were significantly upregulated by DHT in all four models of breast cancer and displayed enrichment of AR, GATA3, and H3K27ac ChIP-seq signals at associated genomic loci." (PMID 38317241, 2024). "Among other cancer types, AR is strongly associated with different forms of breast cancer and the roles of lncRNAs in AR signaling pathways in progression of breast cancer are being increasingly recognized." (PMID 39199690, 2024). "This interaction facilitates the tumor suppressor function of AR and mechanistically explains why AR expression is associated with less proliferative, more differentiated breast tumors and better overall survival in breast cancer." (PMID 38317241, 2024). "Of particular interest were three DNA-binding factors associated with AR on chromatin in all breast cancer contexts: GATA3, JUNB, and ERF." (PMID 38317241, 2024). "AR expression is associated with favorable prognostic factors of breast cancer such as lower histologic grade, ER, and PgR expression." (PMID 39497884, 2024). "Another study revealed the same correlation/association between AR expression and clinical outcomes in ERα-positive breast cancer." (PMID 38339092, 2024). "To further explore the association of AR status and pCR rate, we expanded the analysis in different breast cancer subtypes." (PMID 37099044, 2023). "Nevertheless, AR has been suggested to be a potential therapeutic target for breast cancer, especially for high-risk breast carcinomas that are AR+/ER−." (PMID 37237509, 2023). "USP14 depletion accelerated K48-linked ubiquitination and reduced the stability of the AR protein, which further suppressed the proliferation of AR-responsive breast cancer cells." (PMID 35906484, 2023). "In ER+ breast cancer, previous studies have shown that positive AR status was associated with longer breast-specific survival." (PMID 37345085, 2023). "This indicates that different levels of ER, PR, or HER expressed in the breast cancer cause androgen receptor (AR)-dependent or -independent cancer progression." (PMID 37681860, 2023). "Meanwhile, the association of AR expression and pCR of different breast cancer subtypes was investigated." (PMID 37099044, 2023). "Expression of ER and AR in breast cancer tissues was associated with a decreased infiltration of immune cells into the tumor microenvironment." (PMID 36721218, 2023). "Our results clearly show that in breast cancer cells, ligand-activated intracellular AR upregulates BAD expression and causes its translocation in the nuclei." (PMID 37686282, 2023).
breast carcinoma (continued). "AR expression is reported to be closely associated with clinicopathological features and prognosis of breast cancer." (PMID 37099044, 2023). "The main finding of the results is that HER2-low breast cancer was closely associated with higher HR and AR expression and lower Ki67 index." (PMID 37524746, 2023). "In order to try and untangle the mechanism through which testosterone acts in breast cancer, genetic association studies on tumour subtypes stratified based on AR expression and ER expression are required." (PMID 36209141, 2022). "To further test this, we depleted Kindlin-2 from breast cancer cells and analyzed the effect on the association of Src with AR." (PMID 35595729, 2022). "NCOA1 is known as the “master regulator” of the steroid hormone receptors: estrogen receptor and androgen receptor, which are implicated in breast cancer progression." (PMID 36248436, 2022). "Several studies, including a meta-analysis, showed that the expression of AR in women with breast cancer was associated with better overall and disease-free survival irrespective of ER co-expression." (PMID 35761157, 2022). "AR mutations have been predominantly studied in connection to prostate and breast cancer, especially treatment response." (PMID 35053623, 2022). "The potency of abemaciclib, palbociclib and ribociclib was investigated in a panel of 37 breast cancer cell lines presenting different molecular profiling status, including Rb1 deficiency, ER/AR expression, HER2 amplification, and PIK3CA or BRCA1/2 mutations." (PMID 35813283, 2022). "Additional studies have also implicated a role for an AR-PARP1 signalling axis in breast cancer and have shown that combined inhibition of AR and PARP leads to enhanced antitumour activity by modulating the DDR." (PMID 36376977, 2022). "In HER2 positive breast cancer, AR+ positivity was associated with pCR, but in this study, only 57.3% of patients received trastuzumab." (PMID 35207749, 2022). "A retrospective study suggested that AR expression in luminal–type breast cancer is associated with a better prognosis." (PMID 36556209, 2022). "In summary, our study demonstrated that AR negativity is associated with breast cancers of AA women and that QNBC is an aggressive subtype with an altered gene signature." (PMID 36550153, 2022). "The same approach was further employed to ubiquitinate and deplete the androgen and estrogen receptors (AR and ER), two cancer-associated targets involved in the progression of prostate and breast cancers, respectively." (PMID 36499765, 2022). "Most retrospective studies have found that positive AR expression is associated with a better long–term prognosis of breast cancer." (PMID 36556209, 2022). "In luminal–type breast cancers, high AR expression is associated with a good prognosis, and low ER expression is associated with a poor prognosis." (PMID 36556209, 2022). "In contrast to ER+ breast cancer, high AR expression is associated with a poor prognosis in triple-negative breast cancers (TNBC)." (PMID 34638457, 2021). "More recently, the possibility of using the AR as a predictor marker of breast cancer risk was investigated in a nested case-control study on women with benign breast disease (BBD)." (PMID 35008851, 2021). "Other groups found that 47% of all AR variants in cell-free DNA of breast cancer patients were pathogenic or likely pathogenic." (PMID 34736512, 2021). "In patients with HER2+ breast cancer who underwent neoadjuvant chemotherapy, high AR expression was associated with a better therapeutic response." (PMID 34490107, 2021). "On the other hand, very few reports focus on the potential role of androgens and AR status as markers of breast cancer risk in healthy individuals, and this review was meant to cope with this aim." (PMID 35008851, 2021).
breast carcinoma (continued). "According to some current studies, AR has been confirmed as a biomarker associated with a favorable prognosis of breast cancer in terms of disease-free survival (DFS) and overall survival (OS)." (PMID 34490107, 2021). "Despite this well-documented importance of AR signalling in breast cancer growth and progression, very little is known about the association of androgens, AR expression and breast cancer risk in healthy individuals." (PMID 35008851, 2021). "APP immunoreactivity has been detected in 49 percent of breast carcinoma tissues, and increases in this percentage are associated with androgen receptor in ER-positive breast carcinoma." (PMID 34066808, 2021). "Despite this intricate role in cancer, very little is known about the impact of androgen receptor (AR)-mediated signalling on normal breast tissue and its correlation to breast cancer risk factors." (PMID 35008851, 2021). "Most studies in luminal breast cancers found that AR expression is associated with less aggressive tumor characteristics and extended patient survival." (PMID 34680352, 2021). "While AR is associated with an overall favorable prognosis among women with ER-positive tumors, AR, like ER itself, can support breast cancer progression." (PMID 34736512, 2021). "In breast cancer, AP-2β is associated with favorable clinicopathologic markers such as ER- and AR-positivity and low Ki67, with prolonged event-free survival and the lobular breast cancer subtype." (PMID 34117603, 2021). "Multiple other studies since then have evaluated the utility of AR/ER ratio and shown higher ratios were associated with unfavorable features and poor prognosis in breast cancer." (PMID 34234742, 2021). "The potential correlation between AR structure and breast cancer susceptibility has been investigated in a number of studies." (PMID 35008851, 2021). "AR is expressed in 70–90% of mammary tumors and it has been implicated in all stages of BC development." (PMID 34571711, 2021). "We also investigated the association of AR status with various clinicopathologic features including breast cancer subtypes." (PMID 32290220, 2020). "Recent data in breast cancer suggest that loss of AR signaling through knockdown or pharmacologic inhibition with enzalutamide or seviteronel results in increased sensitivity to ionizing radiation." (PMID 33062889, 2020). "The co-expression of androgen (AR) and estrogen (ER) receptors, in terms of higher AR/ER ratio, has been recently associated with poor outcome in ER-positive (ER+) breast cancer (BC) patients." (PMID 32344660, 2020). "Recently, non-random X-chromosome inactivation and cytosine, adenine, guanine (CAG) repeats on AR genes have been related to increased risk to developing breast cancer." (PMID 32626651, 2020). "In TNBC, AR inhibition has also been shown to modulate the activity of the Ca2+-activated K+ channel, KCa1.1, which is associated with breast cancer invasion and metastasis." (PMID 33062889, 2020). "Given the heightened interest to understand its role in breast cancer, we determined AR expression and assessed its association with clinicopathological parameters among Ethiopian women." (PMID 32374753, 2020). "Here, we show that the molecular subtypes of breast cancer differ in the expression profiles of AR and AR-associated microRNAs." (PMID 32373367, 2020). "In luminal breast cancer patients who had all developed metastatic disease and therefore constituted a bad prognosis patient subset, high AR pathway activity was associated with worse outcome." (PMID 33613616, 2020). "Recently, circulating tumor cells (CTCs) in breast cancer were evaluated for the expression of AR-v7 isoform; the results showed a direct association between AR-v7 expression and increased bone metastasis." (PMID 31952272, 2020). "Although most publications discuss AR as a prognostic marker in breast cancer patients, some reports also found an association between AR and therapy response." (PMID 31728025, 2019).
breast carcinoma (continued). "In post-menopausal breast cancer cases, higher sPSA value was associated with clinic-pathological factors including the expression of AR protein in primary legion." (PMID 31664946, 2019). "In breast cancer, AR expression is associated with improved overall survival regardless of subtype of breast cancer or co-expression of ER." (PMID 34926721, 2019). "We studied androgen receptor (AR) gene expression in primary breast cancer (BC) to determine associations with clinical characteristics and outcomes in the I-SPY 1 study." (PMID 31840050, 2019). "To address the impact of AR mRNA expression levels on prognosis, we compared the risk of relapse among all patients, and within different breast cancer subtypes." (PMID 31728025, 2019). "Recently, androgen receptor (AR) expression has been evaluated in breast cancer, in which AR is associated with cell proliferation and metastasis in ER-negative breast cancer." (PMID 31583246, 2019). "Androgen treatment inhibits ER signaling in ER+/AR+ breast cancer cell lines, and AR expression is associated with improved survival for this subtype in epidemiologic studies." (PMID 30795773, 2019). "In summary, our study underlines, once more, the existence in breast cancer cells of a dynamic interplay between AR and ERα signalling pathways that strictly depends on the hormonal cellular milieu." (PMID 31684907, 2019). "In human breast cancer also, AR overexpression is associated with better outcomes in patients with luminal and triple-negative carcinomas." (PMID 31888566, 2019). "It has been emerged that AR signaling is involved in breast cancer, but dichotomous association of AR with ER status and molecular subtype." (PMID 30975222, 2019). "In this study, we evaluated associations between AR gene expression in primary breast cancer, clinical characteristics, and patient outcomes in a well characterized subset of patients with early stage breast cancer in the I-SPY 1 cohort." (PMID 31840050, 2019). "Hypermethylation of AR promoter was reported to be associated with reduced AR expression in breast cancer cell lines." (PMID 29731982, 2018). "This is reminiscent of the previous study that indicates some association of AR with prognosis of triple negative (TNBC) breast cancer patients." (PMID 29433432, 2018). "Logistic regression models adjusting for the matching factors and BBD lesion type were used to calculate odds ratios (ORs) for the association between AR expression (tertiles: ≤10%, 11–30%, and >30%) and breast cancer risk." (PMID 30276234, 2018). "This study evaluated androgen receptor (AR) expression in normal breast tissue as a potential marker of breast cancer risk." (PMID 30276234, 2018). "On a translational level the recent publication establishing a threshold level for AR positivity is likely to greatly improve clinical parameters associated with AR in breast cancer." (PMID 30416486, 2018). "With hundreds of nuclear receptor co-regulators identified it is beyond the scope of this manuscript to detail all the AR co-regulators however some of which have been implicated in breast cancer are discussed in detail below." (PMID 30416486, 2018). "Recently, 17β-HSD2 expression was found to be closely associated with androgen signaling through binding to the androgen receptor (AR) in breast cancer cells." (PMID 29642629, 2018). "Evidence for a potentiating role of AR in the development of endocrine resistant breast cancer has also been mounting with reports associating high AR expression with poor response to endocrine treatment." (PMID 30416486, 2018). "The positive association between the CD44+/CD24-/low presence and AR expression was more obvious in ER+ breast cancers, which was consistent with our in vitro results." (PMID 29423076, 2018). "Clinically AR protein expression has been associated with a good prognosis in early stage breast cancer." (PMID 30416486, 2018).